THBS1 (thrombospondin 1)
Diseases named in the same sentence as THBS1 in open-access papers (continued):
Sharing a sentence is not in itself a finding about the gene and the disease.
Sepsis (14 papers, 2011 to 2025). Sepsis is defined as life-threatening organ dysfunction caused by a dysregulated host response to infection. "Hence, sepsis caused downregulation of proangiogenic genes such as Vegfa, Nrarp, Jcad and upregulation of the anti-angiogenic gene Thbs1, indicating that the proliferative function of capEC might be disrupted in sepsis." (PMID 34638535, 2021). "ELISA test results indicated that among pediatric patients, the five candidate biomarkers (AT III, CFD, Col1α1, EGFR, Thbs1) all showed varying degrees of decrease in diagnosing sepsis." (PMID 40702576, 2025). "Our findings revealed that Thbs1 is expressed at low levels in the plasma of children with sepsis, making it a viable biomarker for sepsis in this population." (PMID 40702576, 2025). "It has been noted that USF2 knockdown downregulates THBS1 to reduce pyroptosis and further ameliorate sepsis-induced acute kidney injury." (PMID 40220480, 2025). "The results showed that the expression levels of RETN and THBS1 were lower in the survival group, indicating that high expression of RETN and THBS1 is associated with poor prognosis in sepsis." (PMID 37060578, 2023). "The results showed that the expression levels of RETN and THBS1 were lower in the survival group, which indicated that high expression of RETN and THBS1 was associated with a poor prognosis in the sepsis group." (PMID 37060578, 2023). "For example, we observed a significant increase in genes encoding F2rl2, F5, Thbs1, Serpind1 in lung PCV, suggesting that both PCV and capEC are important for coagulation cascade activation in sepsis." (PMID 34638535, 2021). "As a result, the biological function of Thbs1 during sepsis deserves deeper research." (PMID 40702576, 2025). "Cathepsin B (CatB), vascular cell adhesion protein 1 (VCAM-1), neutrophil gelatinase-associated lipocalin (NGAL), protein S100-A9, prosaposin, and thrombospondin-1 levels were significantly increased in the patients with sepsis compared with those of the controls (p < 0.001)." (PMID 39049003, 2024). "Finally, we selected six DEPs that were closely associated with sepsis: cathepsin B (CatB), vascular endothelial cell adhesion molecule (VCAM-1), neutrophil gelatinase-associated lipoprotein (NGAL), protein S100-A9, prosaposin, and thrombospondin-1 (TSP-1)." (PMID 39049003, 2024). "Following CLP-induced sepsis, the plasma abundance of AT III, CFD, EGFR, and Thbs1 was significantly reduced at D1, followed by a gradual increase and recovery, whereas Col1α1 did not exhibit this significant trend." (PMID 40702576, 2025). "The five putative sepsis plasma biomarkers (AT III, CFD, Col1α1, EGFR, Thbs1) revealed certain relationships with clinical laboratory indices related to hematology, biochemistry, blood gas analysis, coagulation function, and immune function." (PMID 40702576, 2025). "In pediatric patients diagnosed with sepsis on D1, plasma levels of AT III, Col1α1, and EGFR were diminished, subsequently increasing progressively, while CFD and Thbs1 remained down on D3 and recovered by D7." (PMID 40702576, 2025). "In conclusion, the present study identified core immune‐related DEGs between severe burns and sepsis, including IL10, RETN, THBS1, FGF13, LCN2 and MMP9." (PMID 37060578, 2023). "Still, the role of THBS1 in the regulation of the PI3K–Akt signaling pathway in cancer is relatively well defined, but its role in sepsis remains to be determined." (PMID 34836493, 2021). "Thrombospondin 1 (THBS1) could mediate cell-to-cell and cell-to-matrix reciprocities which were closely related to the progression of sepsis." (PMID 35003233, 2021). "Thrombospondin-1 (TSP-1) is involved in many biological processes, including immune and tissue injury response, but its role in sepsis is unknown." (PMID 21573017, 2011).
COVID-19 (13 papers, 2021 to 2025). A disease caused by infection with severe acute respiratory syndrome coronavirus 2. "Further experimental analysis strongly suggest that the reduced level of hsa-miR-29a-3p contributes to the excessive expression of THBS1 in severe cases of COVID-19." (PMID 36481664, 2022). "To further validate the bioinformatics results, we performed qRT-PCR analysis for IL17RA and THBS1 in PBMC samples from COVID-19 patients (7 severe and 8 mild patients) and 8 healthy controls." (PMID 36481664, 2022). "In contrast, the expression levels of the THBS1 gene were significantly (P = 0.0009, Wilcoxon rank-sum test) upregulated in the platelets from a severe group of COVID-19 patients." (PMID 36481664, 2022). "These cell adhesion molecules (ANXA1 and ICMA2), cytokine binding and receptor activity genes (CD44, CD45, CD47, CD74, and THBS1), and inflammatory genes (FPR1 and SELL) have been reported to be associated with COVID-19." (PMID 35172892, 2022). "On the other hand, we found that THBS1 expression was mainly in platelets and high in severe COVID-19 patients." (PMID 36481664, 2022). "From the combinatorial analysis of messenger RNA-Seq data of three cohorts, this study discovered that THBS1 was increased in severe COVID-19." (PMID 36481664, 2022). "Additional studies are warranted to examine the role of THBS1 in the disease progression and pathogenesis of COVID-19 and how it is upregulated during coagulation cascades and inflammatory responses." (PMID 36481664, 2022). "COVID-19 research highlights elevated Thbs1 expression in severe patients, where it demonstrates protective effects against pulmonary damage primarily via extracellular matrix protection, inhibition of neutrophil serine proteases, and TGF-β-dependent repair pathways." (PMID 41488667, 2025). "Moreover, platelet factor 4, orosomucoids 1 and 2, as well as platelet α-granule proteins: serglycin, platelet basic protein and thrombospondin 1 were all repressed in plasma six moths after COVID-19." (PMID 39183264, 2024). "On the other hand, the proteins shown in blue were increased in the recovered group, for instance, THBS1, an antiangiogenic protein, which is increased in the serum of asymptomatic COVID-19 patients, as well as other proteins related to endothelial dysfunction or KNG1, a proinflammatory protein." (PMID 37628421, 2023). "These proteins either act as positive regulators of cell death (HBG1, HBB, HBD, and HBA1) or are involved in the cellular response to tumor necrosis factor (FABP4, GPD1, THBS1, ASS1, and PCK2), suggesting that apoptosis may be an important cause of heart failure in patients with COVID-19." (PMID 38087340, 2023). "Moreover, elevated expression levels of IL17RA and THBS1 in the severe COVID-19 patients suggest that those genes could serve as indicators of COVID-19 severity." (PMID 36481664, 2022). "Critically, Thbs1 is upregulated in acute respiratory distress syndrome (ARDS) and coronavirus disease 2019 (COVID-19), where it influences extracellular matrix integrity, neutrophil serine protease activity, TGF-β signaling, and tissue repair." (PMID 41488667, 2025). "Intriguingly, hsa-miR-29a-3p significantly downregulated in severe COVID-19 was predicted to bind the 3′-untranslated regions of both IL17RA and THBS1 mRNAs." (PMID 36481664, 2022). "Based on RNA-Seq datasets, thrombospondin 1 (THBS1) and interleukin-17 receptor A (IL17RA) were significantly upregulated in severe COVID-19 patients’ blood." (PMID 36481664, 2022). "Several altered proteins in the serum of COVID-19 positive asymptomatic donors (FGA, SERPINA1, THBS1) and moreover, in CACs treated with these serum factors (HSPA5, FN1), have been associated with platelet aggregation and coagulation problems." (PMID 35397534, 2022). "Therefore, further studies in a large cohort are warranted to offer novel biomarkers and therapeutic options based on the THBS1, IL17RA, and miR-29a-3p for the treatment of severe COVID-19 patients." (PMID 36481664, 2022).
heart failure (13 papers, 2016 to 2026). Inability of the heart to pump blood at an adequate rate to meet tissue metabolic requirements. "Another target of miR-17 is the connective tissue growth factor (CTGF) and thrombospondin-1 which affects myocardial fibrosis and significant expression of miR-17 has been linked to heart failure and hypertrophic cardiomyopathy." (PMID 36071532, 2022). "This increased expression was further associated with the resistance to heart failure, by reducing thrombospondin-1 (THSP-1) and connective tissue growth factor (CTGF), the two direct targets of members of the miR-17–92 cluster." (PMID 35118144, 2021). "An ELISA specific for the fragmented THBS1 polypeptide will be useful to distinguish the abundance and S-NO levels of functional versus cleaved THBS1 in the PBMCs of patients to predict the risk of heart failure." (PMID 27635260, 2016). "In an animal disease model of hypertrophic cardiomyopathy with a significant enlargement of the left ventricle and severe heart failure, it was shown that both THBS1 and CCN2/CTGF were significantly upregulated in the diseased condition." (PMID 35629393, 2022). "The finding of a significant decrease in full-length THBS1 was also in agreement with the observation of high rate of degradation and secretion of THBS1 during heart failure." (PMID 27635260, 2016). "THBS1, SPP1 and LGR1 were previously associated with cardiomyocyte fibrosis, and heart failure." (PMID 35052347, 2021). "High levels of circulating thrombospondin 1 (THBS1) and THBS2 are correlated with the PAH and poor prognosis of patients with heart failure." (PMID 34638915, 2021). "Previous study shows that up-regulation of THBS1 and THBS4 may lead to matri-cellular protein deposition, and subsequently resulting in DCM, heart failure or death." (PMID 30115125, 2018).
Hyperglycemia (13 papers, 2013 to 2025). An increased concentration of glucose in the blood. "The activation of the latent form of TGFβ1 may be facilitated by commonly hyperglycemia-associated conditions, including metabolic acidosis, oxidative stress, and the increased expression of thrombospondin-1, integrins, or plasmin." (PMID 36430743, 2022). "Blockade of THBS1 has been shown to mitigate hyperglycemia-induced peritoneal fibrosis, while inhibition of THBS1-dependent TGF-β activation reduces renal injury and proteinuria in mouse models of diabetic nephropathy." (PMID 38954467, 2024). "Oxidative stress contributes to antiangiogenic molecule thrombospondin-1 (TSP1) DNA hypomethylation in keratinocytes exposed to hyperglycemia, resulting in overexpression of TSP1 that impairs proper wound healing." (PMID 34249895, 2021). "Microarray analysis revealed that hyperglycemia altered the expression of 30 genes, while hyperglycemia combined with thrombospondin-1 altered the expression of 2822 genes." (PMID 34360550, 2021). "Experimental and clinical studies indicate that hyperglycemia stimulates the production of TGFβ1, thrombospondin 1 (TSP1), and angiotensin II (Ang II) in the diabetic condition." (PMID 25884585, 2015).
Insulin resistance (13 papers, 2012 to 2025). Increased resistance towards insulin, that is, diminished effectiveness of insulin in reducing blood glucose levels. "The protein encoded by THBS1 is an adhesive glycoprotein and proinflammatory cytokine that promotes insulin resistance." (PMID 36544488, 2022). "THBS1 is interesting with respect to type 2 diabetes as it has been shown to be elevated in the circulation in obese and insulin-resistance individuals and loss of THBS1 in mice, protects them from diet-induced weight gain and adipocyte hypertrophy." (PMID 29273013, 2017). "Both collagen type III and thrombospondin 1 expressed in high amounts in adipose tissue have been linked to insulin resistance in fat cells, which may further exacerbate the development of fatty liver." (PMID 39207182, 2024). "For instance, THBS1 expression increases in adipose depots of obese humans and positively correlates with the degree of insulin resistance, while plasma THBS1 concentrations are higher in patients with impaired glucose tolerance." (PMID 38954467, 2024). "Increased expression of THBS1 is in accordance with its potential role in insulin resistance, type 2 diabetes and dyslipidemia, which are known to be involved in developing PCOS1." (PMID 37468508, 2023). "Respectively, the deletion of Thbs1 in mice protects them from insulin resistance and from muscle fibrotic damage in response to HFD." (PMID 37445828, 2023). "MiR-467a-5p, by targeting thrombospondin 1 (THBS1), increases the infiltration of macrophages in adipose tissues, increases the level of IL-6 in adipose tissues, and can prevent insulin resistance." (PMID 35634335, 2022). "Thbs1-null mice were protected against insulin resistance and the inflammation of adipose tissue." (PMID 38255968, 2024). "To validate this results, we assessed the modulation of ICAM1, NQO1, IGFBP3, and THBS1 by POPs because, in addition to their role in cell adhesion, xenobiotic metabolism, angiogenesis, and cancer, these genes were reported to be related to adiposity, insulin resistance, and inflammation." (PMID 22262711, 2012). "In the biological pathway of insulin resistance, the elevated levels of MASP1, THBS1, GPLD1, AAT, HP, RBP4, ZAG, and ApoA-I may be positively correlated with each other, synergistically exacerbating insulin resistance." (PMID 40162315, 2025). "Thbs1 is increased in response to a high-fat diet (HFD) and may induce insulin resistance." (PMID 37445828, 2023).
cardiac hypertrophy (12 papers, 2017 to 2025). "Earlier research has indicated that Thbs1 plays a role in the development of several heart conditions, such as septic cardiomyopathy, cardiac hypertrophy, fatal cardiac atrophy, and damage to heart cells caused by coxsackievirus B3 42, 46-48." (PMID 40084244, 2025). "COL12A1 and THBS1 are genes that, when elevated, can promote fibrosis and cause cardiac remodeling, a hallmark of cardiac hypertrophy." (PMID 32878883, 2020). "In the study, CCN2/CTGF and THBS1 were identified as interesting candidate cardiac hypertrophy biomarkers that are expressed in both the ET-1-induced cardiac hypertrophy in vitro model and the hypertrophic cardiac biopsies at both gene and protein levels." (PMID 35629393, 2022). "In contrast, we found that THBS1 is overexpressed in both the cell-based hypertrophy model and in the cardiac biopsies from patients with cardiac hypertrophy." (PMID 35629393, 2022). "We identified THBS1 as a biomarker candidate for cardiac hypertrophy, since it is overexpressed in both the hiPSC-based hypertrophy model and in biopsies from patients with cardiac hypertrophy." (PMID 35629393, 2022). "It has been suggested that Thbs1 is induced in the pressure-overloaded myocardium given that Thbs1−/− mice have greater cardiac hypertrophy than wild-type mice when submitted to pressure overload stimulation." (PMID 35455758, 2022). "THBS1 has also been observed to be upregulated in another in vitro model of ET-1 induced cardiac hypertrophy." (PMID 32878883, 2020). "This trend is consistent with our results and further supports that Thbs1 may be a key regulatory site in the cardiac hypertrophy–related ceRNA network." (PMID 35211156, 2022). "DUSP1, CCND1, STAT3, and THBS1 play important roles in the pathological process of hypertrophic cardiomyopathy (HCM), regulating myocardial hypertrophy, fibrosis, and cardiac remodelling through a complex signalling network." (PMID 40427439, 2025). "In this paper, we identified and validated two potential cardiac hypertrophy markers, CCN2/CTGF and THBS1." (PMID 35629393, 2022). "Our findings suggest that three mRNAs (Col12a1, Thbs1, and Tgfbr3), four miRNAs (miR-20a-5p, miR-27b-3p, miR-342-3p, and miR-378a-3p), and four related circRNAs (circ_0002702, circ_0110609, circ_0013751, and circ_0047959) may play a key role in cardiac hypertrophy." (PMID 35211156, 2022).
lung adenocarcinoma (11 papers, 2010 to 2025). A carcinoma that arises from the lung and is characterized by the presence of malignant glandular epithelial cells. "It was found that high expression of FN1 and THBS1 was associated with low survival rates in patients with lung adenocarcinoma and lung squamous carcinoma." (PMID 36567906, 2022). "The relationship between FN1 and THBS1 and the survival rate of patients with lung squamous carcinoma and lung adenocarcinoma were also analyzed using the GEPIA database." (PMID 36567906, 2022). "Thrombospondin 1 inversely correlates with invasiveness and lymph node metastasis, and in lung adenocarcinoma cells it has been shown to directly inhibit invasion." (PMID 20515450, 2010). "Analysis of genes co-expressing with THBS1 appeared in three lung adenocarcinoma datasets." (PMID 27513329, 2016). "In summary, THBS1 functions as a tumor suppressor in lung adenocarcinoma." (PMID 27513329, 2016). "We further examined co-expression of RAB32 and THBS1 in lung adenocarcinoma cases from the cancer genome atlas (TCGA, Firehose legacy, 586 samples) and found that mRNA levels of RAB32 and THBS1 positively correlated with each other." (PMID 35884490, 2022). "They reported that SRGN, TPM3, THBS1, HUWE1, and CCDC18 were enriched in lung adenocarcinoma extracellular vesicles." (PMID 30646616, 2019). "mRNA expression levels of THBS1 and THBS2 in lung adenocarcinoma." (PMID 27513329, 2016).